MXI1 (MAX interactor 1, dimerization protein)
Description:
Transcriptional repressor. MXI1 binds with MAX to form a sequence-specific DNA-binding protein complex which recognizes the core sequence 5'-CAC[GA]TG-3'. MXI1 thus antagonizes MYC transcriptional activity by competing for MAX.
Synonyms: bHLHc11; MXD2; MAD2; MXI
Tractability: PROTAC: ubiquitination databases record sites on it.
Gene: Protein-coding gene on chromosome 10 (110,207,605 to 110,287,365, forward strand). Ensembl gene ENSG00000119950.
Subcellular location: Nucleus
Subcellular location (Human Protein Atlas): Nucleoplasm; Cytosol; Nucleoli; Nucleoli rim
Gene Ontology:
Molecular function: DNA-binding transcription repressor activity, RNA polymerase II-specific; protein binding; RNA polymerase II transcription regulatory region sequence-specific DNA binding; DNA-binding transcription factor activity, RNA polymerase II-specific; RNA polymerase II cis-regulatory region sequence-specific DNA binding; protein dimerization activity
Biological process: negative regulation of transcription by RNA polymerase II; regulation of transcription by RNA polymerase II
Cellular component: Mad-Max complex; nucleoplasm; RNA polymerase II transcription regulator complex; chromatin; nucleus
Genetic constraint (gnomAD): Loss-of-function variants: 17 observed, 30.38 expected, observed/expected ratio (o/e) 0.56, 90% interval 0.38 to 0.84. The upper end of that interval is the gene's LOEUF score, 0.84, which puts it in group 3 of 6, group 1 being the genes least tolerant of losing a copy. Missense variants: 295 observed, 357.56 expected, observed/expected ratio (o/e) 0.83, 90% interval 0.75 to 0.91. Synonymous variants: 155 observed, 133.15 expected, observed/expected ratio (o/e) 1.16, 90% interval 1.02 to 1.33.
Homologues: Orthologues: chimpanzee MXI1 (99% identical), macaque MXI1 (99% identical), rat Mxi1 (97% identical), dog MXI1 (96% identical), guinea pig MXI1 (94% identical), mouse Mxi1 (71% identical), rabbit MXI1 (69% identical), zebrafish mxi1 (57% identical), tropical clawed frog mxi1 (56% identical), Caenorhabditis elegans mdl-1 (24% identical). Paralogues in human: MXD1 (42% identical), MXD4 (37% identical), MXD3 (29% identical), MNT (25% identical).
Diseases named in the same sentence as MXI1 in open-access papers:
MXI1 is named in the same sentence as 48 diseases in open-access papers, as found by Europe PMC text mining. Sharing a sentence is not in itself a finding about the gene and the disease. The quoted sentences say what the papers report.
glioma (20 papers, 2002 to 2025). A benign or malignant brain and spinal cord tumor that arises from glial cells (astrocytes, oligodendrocytes, ependymal cells). "Several studies have reported MXI1 mutations in prostate tumor specimens, but these mutations appeared to be rare in both prostate tumors and gliomas." (PMID 24376632, 2013). "The results of [3H]-thymidine incorporation of wild-type and MXI1-transfected U87 clones confirmed that increased Mxi1 expression causes a decreased proliferation rate of glioma cells at different time points." (PMID 11875718, 2002). "To find the miRNAs that may down-regulate MXI1 under pathogenic conditions, we searched for miRNAs that are highly expressed in gliomas according to eight recently published papers." (PMID 24376632, 2013). "However, LOH events at only the ADD3/MXI1 locus provided prognostic significance with a marked reduction in patient survival and appeared to have diagnostic potential in differentiating high-grade gliomas from low-grade ones." (PMID 34970477, 2021). "Studies have shown its potential in promoting glioma cell proliferation by downregulating Max interactor-1 (MXI1), a c-Myc promoter antagonist involved in transcription activation and promoting cell proliferation." (PMID 39795214, 2025). "Regarding glioma, miR-24-3p and miR-27a-3p enhance glioma cell proliferative ability through cooperative regulation of MXI1." (PMID 36718644, 2023). "The ethyl ester form of the FTO inhibitor Meclofenaic (MA2) inhibits FTO and enhances the effect of the chemotherapeutic drug temozolom by targeting the MYC-miR-155/23a cluster-MXI1 feedback circuit in gliomas anti-tumor effects." (PMID 35707365, 2022). "Previous studies have identified several downstream targets of miR-155-5p that function as tumor suppressors in glioma progression, including FOXO3a, MXI1, and HBP1." (PMID 35986010, 2022). "While the tumor-suppressive role of MXI1 in glioma has been reported, less is known about the role of ADD3 in glioma." (PMID 34970477, 2021). "In this study, we showed that LOH at D10S173 (ADD3/MXI1) was frequently seen in high-grade gliomas compared with low-grade gliomas and with a high proliferative index, and the results were suggestive of the role of these genes in regulating tumor progression." (PMID 34970477, 2021). "Through this study, it is possible that MXI1 can also suppress the glioma through LUZP2 which is still to be explored." (PMID 32695826, 2020). "In fact, previous studies have reported that miR-155, a GBM progression-related miRNA, can promote glioma cell proliferation by regulating MXI1." (PMID 29312626, 2017). "In particular, it has been recently shown to promote glioma cell proliferation via the regulation of MXI1 and GABA receptors." (PMID 25986346, 2015). "MiR-27a-3p was found to promote cell proliferation in glioma cells via cooperative regulation of MXI1." (PMID 24373112, 2014). "All these results suggest that MXI1 is a direct target of miR-155, and this enhances our understanding of the mechanisms of MXI1 down-regulation in glioma cells." (PMID 24376632, 2013). "The potential role of miR-155 in promoting glioma cell proliferation by targeting MXI1 was confirmed in various glioma cell lines by rescue experiments using MTT assays, EdU incorporation assay, and cell counting experiments." (PMID 24376632, 2013). "Given the tumor suppressor effect of MXI1, we studied the potential role of miR-155 in glioma cell proliferation by directly counting cell number and performing MTT and EdU incorporation assays." (PMID 24376632, 2013). "In summary, from screening a panel of up-regulated miRNAs in glioma, miR-155 was found strongly to target MXI1, which is a tumor suppressor gene that is down-regulated in gliomas." (PMID 24376632, 2013). "To evaluate the role of MXI1 in gliomas, we first determined the expression level of MXI1 in A172, U87 and U251 glioma cells by quantitative reverse transcription-PCR (qRT-PCR)." (PMID 24376632, 2013).
glioma (continued). "The strongest inhibitory miRNA, miR-155, can attenuate the activity of a luciferase reporter gene that is fused with the MXI1 3′UTR and decrease the expression levels of MXI1 mRNA and protein in U87 glioma cells." (PMID 24376632, 2013). "To study the deregulation of MXI1 in gliomas, we initially predicted two miR-155 binding sites in the MXI1 3′UTR using miRanda and microRNA.org." (PMID 24376632, 2013). "Consistent with this, in the G2/M phase, the overexpression of MXI1 promotes the differentiation of glioma cells and decreases the cell proliferation via repressing the cyclin B1 gene expression during transcription." (PMID 24376632, 2013). "In this study, we discovered that there is a decreased expression of MXI1 in three different glioma cell lines by qRT-PCR." (PMID 24376632, 2013). "In this study, we show that the relative expression level of MXI1 is markedly down-regulated in glioma cell lines." (PMID 24376632, 2013). "The level of MXI1 mRNA is significantly lower in glioma cell lines than the level in human normal brain tissues." (PMID 24376632, 2013). "Given that MXI1 is functionally targeted by miR-155 in glioma cells, we analyzed the expression level of miR-155 and MXI1 mRNA in 18 sets of glioblastoma multiforme specimens and their corresponding normal adjacent tissues specimens by qRT-PCR." (PMID 24376632, 2013). "The expression of miR-155 and MXI1 in glioma samples was analyzed and showed a significant inverse correlation." (PMID 24376632, 2013). "The data suggest that Mxi1 that interacts with Max can antagonize Myc and thereby suppress glioma progression." (PMID 22348395, 2012). "Overexpression of Mxi1 in human glioma cell lines reduces their mitotic activity, possibly through down-regulation of cyclin B1 expression." (PMID 22348395, 2012). "To test the role of Mxi1 on tumorigenesis of glioma cells we transfected a CMV-driven MXI1 cDNA in U87 human glioblastoma cells." (PMID 11875718, 2002). "miR-155 is involved in glioma proliferation via downregulation of Max interactor-1 (MXI1) factor." (PMID 39795214, 2025). "As reported in previous studies, miR-24-3p could regulate the expression of MXI1 and improve the proliferation of glioma cells." (PMID 33675584, 2021). "Moreover, it promotes glioma cell proliferation via regulation of MXI1, glioma cell invasion by inhibiting the expression of HOXD10, and cell growth via targeting apoptotic protease activating factor‐1." (PMID 28248456, 2017). "We hypothesized that some miRNAs, especially up-regulated miRNAs, might be responsible for the low expression of MXI1 in gliomas." (PMID 24376632, 2013). "MXI1 is located at 10q24-25 a region where loss of heterozygosity (LOH) has been reported to occur in several human cancers, including prostate tumors, renal cell carcinomas, meningiomas, endometrial cancers, small-cell lung cancers and gliomas." (PMID 24376632, 2013). "In this study, we demonstrated that the expression level of MXI1 was very low in glioma cell lines." (PMID 24376632, 2013). "The effect of miR-155 on MXI1 was also confirmed in U87 glioma cells." (PMID 24376632, 2013). "Together, these results indicate that miR-155 promotes glioma cell proliferation partially by down-regulating the expression of MXI1; this result suggests that MXI1 could be a new functional target of miR-155 in glioma formation." (PMID 24376632, 2013). "Moreover, miR-24-3p promoted cell proliferation in glioma cells via cooperative regulation of MXI1." (PMID 29632473, 2018). "Therefore, we speculated that some miRNAs may be responsible for the low expression of MXI1 in gliomas." (PMID 24376632, 2013). "we found that SAMD8, RER1, MXI1, and CHI3L1 were highly expressed in most of the glioma tumor microenvironment cells." (PMID 37934565, 2023).
glioma (continued). "In this pathway, MYC inhibits the expression level of MXI1 by affecting the expression of miR-155 and miR-23a, and MXI1 can also inhibit the expression level of MYC, thus forming a feedback loop to regulate glioma tumorigenesis and cell proliferation." (PMID 35688823, 2022). "Another identified factor, MXI1, was reported as a tumor suppressor negatively regulating c-MYC and an inhibitor of glioma proliferation." (PMID 34131149, 2021). "Recently, Max interactor-1 (MXI1), an antagonist of c-Myc that is involved in brain tumor progression, has been reported to be deregulated in a variety of tumors including glioma." (PMID 24376632, 2013). "Therefore, miR-155 may promote the proliferation of glioma cells by directly targeting MXI1." (PMID 24376632, 2013). "However, the mechanism of MXI1 deregulation in gliomas remains unclear." (PMID 24376632, 2013). "Taken together, these data suggest that miR-155 directly targets MXI1 via its 3′UTR in 293T and U87 glioma cells." (PMID 24376632, 2013).
prostate carcinoma (9 papers, 1997 to 2022). A carcinoma that arises from epithelial cells of the prostate gland. "MXI1 negatively controls the activity of Myc oncoprotein so that it can function as a tumor suppressor in prostate cancer." (PMID 33773548, 2021). "It was also proven that MXI1 suppresses prostate tumour cell proliferation supporting a role in the pathogenesis of human prostate cancer." (PMID 32784653, 2020). "Infection of cultured DU145 prostate cancer cells with adenovirus expressing MXI1 resulted in decreased cell proliferation and a higher proportion of cells in the G /M phase of the cell cycle, and decreased c-MYC expression by MXI1 resulted in cell growth arrest." (PMID 35602303, 2022). "In this study, although there is no confirmation of gene-target interactions by in vitro or in vivo methods, reviewing the results of bioinformatic analyzes and previous studies, we suggest that down-regulated MXI1 plays pivotal role during prostate cancer development." (PMID 33773548, 2021). "MXI1, the only prognostic marker among the studied genes, is a transcriptional repressor and a tumour suppressor gene, because it acts as an antagonist of the oncogene c-Myc, which is overexpressed in many cases of prostate cancer." (PMID 32784653, 2020). "No mutations were found in these two important coding regions and we therefore conclude that MXI1 does not make a major contribution to prostate cancer susceptibility." (PMID 9376279, 1997). "To investigate the possibility that MXI1 may be involved in inherited susceptibility to prostate cancer, we have sequenced the HLH and ZIP regions of the gene in 38 families with either three cases of prostate cancer or two affected siblings both diagnosed below the age of 67 years." (PMID 9376279, 1997). "Importantly for six of the eight candidates, (TRIB1, PCA3, GRHL2, ACTG2, GSN, and MXI1) we were able to confirm the differential expression of the genes that harbor these STRs using a large dataset of prostate cancers compared to adjacent non-malignant cells." (PMID 29203868, 2017).
breast cancer (8 papers, 2011 to 2025). A primary or metastatic malignant neoplasm involving the breast. "Mxi1 knockout mice are prone to squamous cell carcinoma and malignant lymphoma, and higher MXI1 protein levels are associated with better breast cancer prognosis." (PMID 35602303, 2022). "Noteworthy, a recently proposed model of MYC-dependent signal transfer from breast cancer cells to the surrounding cancer-associated fibroblasts involves exosome-transported miR-105, which downregulates the expression of MXI1, an inhibitor of MYC activity, and results in an increased MYC activity." (PMID 36140779, 2022). "c-MYC and MXI1 proteins may selectively bind the A-allele in breast cancer, although this study utilized two genetically distinct cell lines rather than isogenic lines." (PMID 33918978, 2021). "In another study by Lofsted and coworkers it was demonstrated that hypoxia upregulates Mxi-1 mRNA and protein in neuroblastoma and breast cancer cells, and Mxi-1 was confirmed as a direct HIF-1α target gene." (PMID 21925595, 2011). "The exosomal miR-105 secreted by breast cancer (BC) targets MXI1, activates the MYC pathway in CAFs, enhances the glycolysis and glutamine decomposition of CAFs, and detoxifies the metabolites (lactate and NH4 +) to fuel adjacent cancer cells." (PMID 36899389, 2023). "UBE2O promotes the proliferation, epithelial-mesenchymal transformation, and stemness properties of breast cancer cells through the UBE2O/AMPKα2/mTORC1 positive feedback loop, and UBE2O facilitates tumorigenesis and radioresistance by promoting Mxi1 ubiquitination and degradation." (PMID 35668470, 2022).
glioblastoma (8 papers, 2002 to 2022). The most malignant astrocytic tumor (WHO grade IV). "First, we demonstrate that Mxi1 over-expression causes an inhibition of proliferation of U87 glioblastoma cells in vitro due to an accumulation of the cells in the G2/M phase of the cell cycle." (PMID 11875718, 2002). "MXI1 acted as a tumor suppressor in human glioblastomas involving the transcriptional downregulation of cyclin B1 gene expression." (PMID 32695826, 2020). "At the same time, we determined that the level of MXI1 mRNA was inversely correlated with miR-155 expression in glioblastoma multiforme specimens." (PMID 24376632, 2013). "To further understand the role of miR-155, we quantified the expression of miR-155 and MXI1 in 18 sets of glioblastoma multiforme specimens and their corresponding normal adjacent tissues." (PMID 24376632, 2013). "The over-expression of Mxi1 in glioblastoma cells suppresses cell growth, inducing an accumulation of the cells in the G2/M phases of the cell cycle." (PMID 11875718, 2002). "In the present study we describe one molecular mechanism by which Mxi1 can act as a tumour suppressor in glioblastomas." (PMID 11875718, 2002). "Here we demonstrate that during the Mxi1-induced G2/M block in glioblastoma cells, the expression of the master regulatory gene of the G2 progression, cyclin B1 is down-regulated at transcriptional level, indicating that cyclin B1 is a target of Mxi1 activity." (PMID 11875718, 2002). "U87 cells, a cell line derived from a human glioblastoma, were stably transfected with a construct carrying MXI1 cDNA." (PMID 11875718, 2002). "Furthermore, we determined the expression levels of MXI1 and miR-155 in 18 sets of glioblastoma multiforme specimens and paired normal tissue specimens." (PMID 24376632, 2013). "In addition, we determined that the level of MXI1 mRNA was inversely correlated with the expression of miR-155 in 18 sets of glioblastoma multiforme specimens." (PMID 24376632, 2013). "MXI1 gene has been mapped to the chromosome region 10q25, frequently deleted in glioblastomas." (PMID 11875718, 2002). "Thus, our findings indicate that Mxi1 can act as a tumour suppressor in human glioblastomas through a molecular mechanism involving the transcriptional down-regulation of cyclin B1 gene expression." (PMID 11875718, 2002). "In conclusion, we have reported that the molecular mechanism through which Mxi1 can act as an inhibitor of proliferation and tumorigenesis of U87 glioblastoma cells includes the inhibition of cyclin B1 promoter activity through the E-box and the possible consequent loss of cyclin B1 accumulation." (PMID 11875718, 2002). "FTO upregulated the MYC level, known as proto-oncogene TF, and downregulated the expression of MAX interactor 1 (MXI1), which binds to the MYC promoter and inhibits its expression, playing an oncosuppressor role in glioblastoma." (PMID 36012529, 2022). "There have been a number of isoforms of MXI1 isolated from glioblastoma and haematological cells that suggest dominant negative activity; antagonising the normal activity of MXI1 and demonstrating differential expression." (PMID 18493233, 2008). "The investigation of the mxi1 coding sequence in primary glioblastomas does not identify this gene as a major target on chromosome 10q." (PMID 11875718, 2002).